CRP (C-reactive protein)
Diseases named in the same sentence as CRP in open-access papers (continued):
Sharing a sentence is not in itself a finding about the gene and the disease.
urinary tract infection (103 papers, 2010 to 2026). "A logistic regression analysis was conducted to analyse the association of age, positive maternal vaginal swab, CRP, neutrophil count, urine chemical test and the occurrence of Serious Bacterial Infections (SBIs) and Urinary Tract Infections (UTIs)." (PMID 41065831, 2025). "Previous studies reported a significant association between CRP levels and lower urinary tract symptoms in women and men, and subsequently among urinary tract infection patients." (PMID 34187385, 2021). "In our study, more than 50% of DF patients with CRP>50 mg/L had an associated bacterial infection, such as otitis, sinusitis or urinary tract infection." (PMID 24069477, 2013). "Significantly higher CRP, procalcitonin levels, and leukocyte counts in this group suggested that stone-related obstructive uropathy might be associated with superimposed infection of the urinary tract." (PMID 34880338, 2021). "The wait time before surgery could be increased because of the evaluation of CRP progression or underlying pulmonary or urinary tract infection." (PMID 29854731, 2018). "Moreover, respiratory and urinary tract infections, as the causes of acute abdominal pain in children, may often accompany by elevated levels of leukocytes and CRP." (PMID 32953890, 2020). "Addition of calprotectin to CRP significantly increased the AUC for lower versus upper respiratory tract infection and lower respiratory tract infection versus urinary tract infection." (PMID 42281890, 2026). "Some (38%, n = 11) ICBs also used diagnostics tests to improve prescribing, such as tests for urinary tract infections (UTIs), C-reactive protein (CRP) and procalcitonin (PCT) in certain situations." (PMID 41409989, 2025). "In our study, 14% of young febrile infants received a diagnosis of urinary tract infection; in this population, using an optimal cut-off of 21.65 mg/L, CRP showed moderate discriminative power (AUC = 0.75) in differentiating UTI." (PMID 41065831, 2025). "A notable fivefold increase in CRP serves as a significant predictor of acute renal colic combined with urinary tract infection." (PMID 38281018, 2024). "The NICE guidelines for urinary tract infection advised against using CRP alone to differentiate between pyelonephritis and cystitis in children." (PMID 38504318, 2024). "These include urine dipsticks to diagnose urinary tract infections, rapid throat tests to identify Group A Streptococcal infections, and C-reactive protein (CRP) POC tests." (PMID 36823597, 2023). "It was discussed that increased CRP (>200 mg/L) can be seen in urinary tract infections, and also, elevated values (≥30 mg/L) was seen in the majority of nonpregnant and pregnant women with acute pyelonephritis." (PMID 37873776, 2023). "Aimed to explore the relationships between infection localization, bacterial species, and procalcitonin (PCT) and C-reactive protein (CRP) levels in urinary tract infections (UTIs)." (PMID 37821527, 2023). "In fact, clinically apparent infections (including respiratory infection, urinary tract infection and cholecystitis) or laboratory signs of inflammation, such as an increase in CRP levels or BSR, preceded or accompanied most episodes of clinical deterioration." (PMID 35907972, 2022). "If a patient is experiencing symptoms of urinary tract infections after biopsy urine cultures and CRP tests are common investigations." (PMID 35930069, 2022). "The more representative infectious complication in our study was urinary tract infection, which can be an explanation for the low CRP cut-off value on PODs 7-10." (PMID 36387256, 2022). "In our study, typical signs of urinary tract infections, positive urinary cultures, elevated CRP and leucocytes in urine were all more common after SB than MRI-TB." (PMID 35930069, 2022). "The only subgroup that showed a positive correlation between GLP‐1 and CRP were patients with urinary tract infection with Escherichia coli." (PMID 36117310, 2022).
urinary tract infection (continued). "Women experienced a range of vaginal and urinary tract infections, caries, and scabies, and showed evidence of low-grade inflammation based on CRP." (PMID 36079755, 2022). "Vital signs, presepsin, PCT, CRP, white blood cell (WBC) count, causative agents of urinary-tract infections, and other data were evaluated on the enrollment, third, and fifth days." (PMID 34641833, 2021). "One patient was excluded due to the combination of CRP elevation and an acute venous leg ulcer and another one due to a still active urinary tract infection in antibiotic treatment at the time of measurement." (PMID 34764926, 2021). "For pyelonephritis, C-reactive protein < 20 mg/l had LR- of 0.10 (95%CI 0.04–0.30) to 0.22 (95%CI 0.09–0.54) in children with signs suggestive of urinary tract infection." (PMID 34565335, 2021). "In the current study we assessed the ability of the biomarkers PCT, MR-proADM and CRP in predicting treatment failure in a randomized trial of antibiotic treatment duration (i.e. 7 versus 14 days) in patients with febrile urinary tract infection." (PMID 30764769, 2019). "This variability in WAZ recovery was not predicted by baseline age, anthropometry, breastfeeding status, salivary CRP, amount consumed at the test meal, presence of diarrhoea or a urinary tract infection." (PMID 29092084, 2018). "Previous studies showed that blood CRP concentration was significantly higher in patients with urinary tract infection and interstitial cystitis, which gained specific attentions in bladder dysfunction recently." (PMID 26879937, 2016). "The same day treatment with cefotaxime was started for suspected urinary tract infection accompanied by a C-reactive protein (CRP) level of 68 mg/L." (PMID 26980436, 2016). "Serum amyloid-A (SAA) and C-reactive protein (CRP) appear to be the most reliable markers for antimicrobial therapy monitoring in patients with urinary tract infections." (PMID 26587339, 2015). "C-reactive protein was normal or only slightly elevated due to a urinary tract infection and gastritis." (PMID 25175670, 2014). "The data of 21 patients (22 arteries) had to be excluded due to missing follow-up data, additionally 5 patients (5 arteries) with clinical signs of pulmonary or urinary tract infections and/or markedly elevated CRP levels or leukocyte counts were excluded." (PMID 21829478, 2011). "The mother has been hospitalized for four days due to a urinary tract infection and preterm premature rupture of membranes (pPROM), 90 h, treated with ampicillin and erythromycin devoid of leucocytosis and increased C-reactive protein (CRP) levels." (PMID 40538937, 2025). "Two patients who did not qualify as treatment success had an efficacy score of 3 (inconclusive): with CRP elevation due to concurrent urinary tract infection and a small CRP pre-value in one patient each, and these were not judged as treatment failures for PVO." (PMID 37158826, 2023). "Some factors that have been associated with antibiotic prescriptions in pediatric emergency departments were the presence of a fever peak higher than 40 C, abnormal lung sounds, increased C-reactive protein, a diagnosis of respiratory tract infections, and urinary tract infections." (PMID 37237820, 2023). "As a result, urinary tract infections caused with MRSA, extended-spectrum β-lactamases producing organisms (ESBL), vancomycin-resistant enterococci (VRE), and the carbapenem-resistant organisms (CRE/CRP) have higher morbidity and mortality." (PMID 33622320, 2021). "At that time, the patient presented chills and dysuria, with marked increase of inflammatory markers (CRP 16.5 mg/dl; procalcitonin 1.46 ng/ml, r.v. < 0.5), probably due to acute urinary tract infection in a catheterized patient, and antibiotic therapy (amoxicillin/clavulanate) was started." (PMID 32477142, 2020).
urinary tract infection (continued). "This relapse was associated with a urinary tract infection (without systemic signs of inflammation, i.e. without leucocytosis, fever or elevated C-reactive protein (CRP) levels) which we successfully treated according to local guidelines." (PMID 25516429, 2014). "However, in scenarios such as urosepsis or urinary tract infections (UTIs), urinary CRP levels may surge due to the presence of blood in urine or urine densification, a phenomenon often tied to creatinine levels (typically ranging from 0.7 to 1.3 mg/mL)." (PMID 39143107, 2024). "Three participants were excluded because their CRP levels were above 10 μg ml−1 at all measure points (that is, indicating acute inflammation; n=1), invalid blood samples for almost all measures (n=1), or a retrospective report showed chronic urinary tract infection during the study phase (n=1)." (PMID 28509904, 2017). "Inflammatory markers, including levels of C-reactive protein (CRP), procalcitonin, and leukocyte counts, were also significantly higher in patients with urolithiasis or other causes, suggesting that these patients might have superimposed urinary tract infection." (PMID 34880338, 2021). "Kawasaki disease (KD) is sometimes confused with urinary tract infection (UTI) because both can present with pyuria and C-reactive protein (CRP) elevation." (PMID 30454066, 2018). "The admission laboratory values of leukocytes (SMD = 0.366) and CRP (SMD = 0.328), urinary tract infection (SMD = 0.349), ICU treatment (SMD = 0.373), Life satisfaction (at baseline: SMD = 0.493; at follow-up: SMD = 0.373), and mortality (SMD = 0.489) showed considerable differences." (PMID 39953428, 2025). "Although there was no elevation in C-reactive protein (CRP), bacteriuria and abdominal CT showed elevated perirenal fat tissue density on both sides, leading to a diagnosis of urinary tract infection." (PMID 39897293, 2025). "In our center, we ensure that prior to surgery, no urinary tract infections or systemic infections (determined with C-reactive protein, leukocyte count, fever) are present." (PMID 38514531, 2024). "Data on pyelonephritis seem contrasted, but another study concluded that higher CRP is not accurate in localizing the site of urinary tract infections in young women without clinical signs of acute pyelonephritis." (PMID 37873776, 2023). "Other infections can also increase the patient’s CRP level—e.g., infections such as urinary tract infection or upper respiratory tract infection, which have no connection to wound healing." (PMID 35011910, 2021). "A new serum marker of inflammation copeptin (CPP) a stable C-terminal pro-vasopressin was assessed along with conventional markers such as C-reactive protein (CRP), procalcitonin (PCT) and IL-6 to discriminate between lower and upper bacterial urinary tract infections (UTI)." (PMID 26152182, 2015). "In addition, clinical data from patients with endocarditis, urinary tract infection, noninfectious and postoperative inflammation show divergent correlations between inflammation (using CRP) and GLP‐1." (PMID 36117310, 2022). "Elevated CRP levels are commonly observed in chronic SCI, attributed to clinical factors such as pressure ulcers, urinary tract infections, lack of physical activity, and accumulation of adipose tissue." (PMID 38571922, 2024). "Laboratory results were significant for neutrophilic leukocytosis, microcytic anemia, mild transaminitis, and elevated ESR and C-reactive protein (CRP); urinalysis was positive for leukocytes, erythrocytes, and bacteriuria with no symptoms of urinary tract infection." (PMID 39996173, 2025). "Furthermore, the lack of data on participants' urinary tract infections poses a constraint on our ability to investigate the relationship between C-reactive protein (CRP) and kidney stones specifically in individuals without urinary tract infections." (PMID 38281018, 2024).
urinary tract infection (continued). "However, at the same time, it is a pitfall in the misdiagnosis of KD as urinary tract infection (UTI), especially in a febrile child who does not show the typical features of KD but does have pyuria and C-reactive protein (CRP) elevation." (PMID 30454066, 2018).
spondylitis (102 papers, 2012 to 2026). The inflammation of a vertebra. "It has been reported that the prevalence of AS patients with bone loss is about 25% and low vertebral bone mineral density in AS is closely associated with high modified Stoke Ankylosing Spondylitis Spinal Score (mSASSS) and C-reactive protein (CRP)." (PMID 34879876, 2021). "The aim was to determine the number of patients with Ankylosing Spondylitis Disease Activity Score with C-reactive protein (ASDAS-CRP) of <2.1 (inactive/moderate disease activity)." (PMID 39440784, 2025). "The Ankylosing Spondylitis Disease Activity Score with C-reactive protein (ASDAS-CRP) was calculated for all AS patients; scores ≥ 2.1 indicated high disease activity, while < 2.1 indicated low disease activity." (PMID 41423295, 2025). "These guidelines designate Ankylosing Spondylitis Disease Activity Score with C-reactive protein (ASDAS-CRP) for assessing patients' response to treatment." (PMID 39440784, 2025). "Tim-3 expression on neutrophils was higher in AS patients than in HC, showing a positive correlation with erythrocyte sedimentation rate (ESR), c-reactive protein (CRP), and Ankylosing Spondylitis Disease Activity Score (ASDAS)." (PMID 40182847, 2025). "The primary outcome is the change in Ankylosing Spondylitis Disease Activity Score with C-reactive protein (ASDAS-CRP) at 24 weeks." (PMID 40623300, 2025). "A phase 3 trial demonstrated a 26% major improvement in Ankylosing Spondylitis Disease Activity Score - CRP (ASDAS-CRP) scores with tofacitinib 10 mg daily." (PMID 41209988, 2025). "Disease activity was assessed using the Ankylosing Spondylitis Disease Activity Score with ESR or CRP (ASDAS-ESR/CRP) and Bath Ankylosing Spondylitis Disease Activity Index (BASDAI)." (PMID 39415300, 2024). "Demographic and clinical data, alongside standard outcome measures for axSpA, including the BASDAI, BASFI, BASMI and Ankylosing Spondylitis Disease Activity Score using CRP (ASDAS-CRP) were collected." (PMID 38414917, 2024). "Remission and LDA rates obtained at 24 months according to the Ankylosing Spondylitis Disease Activity Score based on C-reactive protein (ASDAS-CRP) scale, as well as the safety profile, were compared between the two groups." (PMID 39469413, 2024). "It was combined with age, CRP level, functional status as assessed by the Bath Ankylosing Spondylitis Functional Index (BASFI) and the presence of enthesitis." (PMID 36574181, 2023). "Effectiveness was assessed using Ankylosing Spondylitis Disease Activity Score with C-reactive protein (ASDAS-CRP) and Disease Activity in Psoriatic Arthritis (DAPSA) Score." (PMID 37936691, 2023). "Of all patients with axSpA, serum anti-Kaiso autoantibody levels were positively correlated with the C-reactive protein level and the Bath Ankylosing Spondylitis Disease Activity Index score and negatively correlated with disease duration." (PMID 37063878, 2023). "Patients with SpA with uveitis had higher trend of Ankylosing Spondylitis Disease Activity Score (ASDAS)-CRP and BASDAI." (PMID 37679498, 2023). "CRP has therefore been included in the Ankylosing Spondylitis Disease Activity Score (ASDAS-CRP), which is currently used to assess disease activity in SpA." (PMID 31276001, 2019). "The Ankylosing Spondylitis Disease Activity Score on the basis of CRP (ASDAS-CRP) can assess the disease activity and efficacy of different therapies in AS." (PMID 27449221, 2016). "Regarding axSpA, an observational study conducted on 110 patients showed an improvement in disease activity as measured by Ankylosing Spondylitis Disease Activity Score with CRP (ASDAS-CRP), which was more frequent in the group of patients following a MD pattern than in the control group." (PMID 40284245, 2025).
spondylitis (continued). "The Ankylosing Spondylitis Disease Activity Score with CRP (ASDAS-CRP) has emerged as a preferred tool for disease assessment in current practice recommendations due to its longitudinal correlation with syndesmophyte formation, which influences spinal mobility." (PMID 39415300, 2024). "In addition, inverse correlations of DUSP22 gene expression in peripheral T cells with C-reactive protein, erythrocyte sedimentation rate, and Bath Ankylosing Spondylitis Disease Activity Index (BASDAI) were observed (all p < 0.05)." (PMID 36765305, 2023). "The clinical data of both tender, swollen joint counts, erythrocyte sedimentation rate, C-reactive protein, white blood cell counts, and disease activity using Bath Ankylosing Spondylitis Disease Activity Index (BASDAI) and Disease Activity Index for Psoriatic Arthritis (DAPSA), were recorded." (PMID 37685529, 2023). "Clinical laboratory tests, such as WBC count, ESR, and CRP level, which are all nonspecific in showing infectious processes and linked to spondylitis in the majority of cases, are a significant part of clinical diagnoses." (PMID 36684365, 2022). "In addition, the magnitude of the Ankylosing Spondylitis Disease Activity Score—C-Reactive Protein (ASDAS-CRP) index was found to directly correlate with peripheral blood ILC3 count." (PMID 36355542, 2022). "The objective of the study was to validate the Ankylosing Spondylitis Disease Activity Score (ASDAS) based on a quick quantitative C-reactive protein (qCRP) assay (ASDAS-Q) in a multicentre, prospective, cross-sectional study in patients with axial spondyloarthritis (axial SpA)." (PMID 35368376, 2022). "Disease activity may be evaluated in RA by the Disease Activity Score 28—erythrocyte sedimentation rate (DAS28-ESR) and in axSpA by the Ankylosing Spondylitis Disease Activity Score—C reactive protein (ASDAS-CRP)." (PMID 30782174, 2019). "To check whether a novel, more objective measures of disease activity would have more bearing on the results, we retrospectively substituted BASDAI with the Ankylosing Spondylitis Disease Activity Score incorporating the CRP level (ASDAS-CRP)." (PMID 23509994, 2013). "Disease activity was assessed using the Bath Ankylosing Spondylitis Activity Index (BASDAI) (range, 1–10), Maastricht Ankylosing Spondylitis Enthesitis Score (MASES) (range, 1–13), and C-reactive protein (CRP) concentration (mg/dl)." (PMID 39733199, 2024). "Outcomes assessed were ≥ 20% improvement in the Assessment of Spondyloarthritis International Society Criteria (ASAS20) and change from baseline in Bath Ankylosing Spondylitis Functional Index (BASFI) and C-reactive protein (CRP) at weeks 12–16." (PMID 32107666, 2020). "Mean baseline scores for Bath Ankylosing Spondylitis Disease Activity Index (BASDAI) ranged from 4.4 to 7.6 cm, for BASFI ranged from 3.2 to 7.4 cm, and for CRP ranged from 6.2 to 32.0 mg/l." (PMID 32107666, 2020). "Plasma CRP is a central marker used in combination with 28-joint Disease Activity Score (DAS28CRP) and Ankylosing Spondylitis Disease Activity Score (ASDAS) to determine disease progression and treatment success, that correlates to disease progression." (PMID 32782445, 2020). "Construct convergent validity was evaluated by correlating SASDAS with ASDAS CRP/ESR, BASDAI, Bath Ankylosing Spondylitis Functional Index (BASFI) and EuroQol five-dimensional (EQ-5D) questionnaire." (PMID 25146299, 2014). "Median CRP (IQR) values were higher (3.9 (1.0; 8.0) vs. 2.4 (1.0; 7.2)) and the impairment of spinal mobility according to the median BASMI (Bath Ankylosing Spondylitis Metrology Index, IQR) more severe in patients with elevated anti-CD74 Abs (1.3 (0.0, 3.0) vs. 1.0 (0.0, 2.0))." (PMID 40063233, 2025).